CRP (C-reactive protein)
Diseases named in the same sentence as CRP in open-access papers (continued):
Sharing a sentence is not in itself a finding about the gene and the disease.
autoimmune disease (continued). "In particular, we evaluated the diagnostic performance of GLB, AGR, fibrinogen, ESR, and CRP in patients with venous thrombosis, autoimmune diseases, malignancies, and concurrent infections in other organs based on the optimal threshold." (PMID 34172035, 2021). "Other markers were CRP for inflammation and cardiovascular risk, sCD27 associated with lymphocyte activation in autoimmune diseases, and anti-C1q associated with nephritis in SLE." (PMID 28116147, 2016). "C-reactive protein (CRP) is the major acute-phase protein involved in the resistance to microbes and autoimmune diseases and is an important risk marker of cardiovascular and cerebrovascular disorders." (PMID 27738642, 2016). "For example, C reactive protein (CRP) is a particularly valuable biomarker of inflammation which is overexpressed during inflammatory responses caused by an infection, by autoimmune diseases like lupus and RA, or in some cancers." (PMID 26346739, 2015). "Multivariable logistic regression confirmed that CRP (P = 0.002), white blood cell count (P < 0.001), hemoglobin (P = 0.015), and female gender (P < 0.001) are independent risk factors for autoimmune disease in patients with high IgG levels." (PMID 24180594, 2013). "This meta-analysis provides first-time evidence that chronic elevation of CRP in autoimmune diseases may be associated to an increased risk of later development of neuroinflammation and possibly dementia." (PMID 36776896, 2023). "Since other causes of CRP elevations (such as autoimmune diseases) are very rare in the neonatal period, we think that classifying infants based on repeated CRP measurements as well as blood cultures brings a better distinction between infected and uninfected cases." (PMID 36233375, 2022). "Some studies have shown an association between CRP and autoimmune diseases." (PMID 34799942, 2022). "We evaluated the diagnostic accuracies of GLB, AGR, fibrinogen, ESR, and CRP in patients with comorbidities (venous thrombosis, autoimmune diseases, malignancies, and concurrent infections in other organs) separately and found that their diagnostic accuracies were good." (PMID 34172035, 2021). "The higher CRP among the four anti-centromere B positive Kitavans could thus signal inflammatory activity in an associated autoimmune disease but could also signal inflammatory activity in an anti-centromere B autoantibody-inducing infectious disease." (PMID 33334321, 2020). "Likewise, the levels of acute-phase reactants such as ESR and CRP were comparable, and so was the frequency of positive anti-nuclear antibodies and associated autoimmune diseases." (PMID 31019511, 2019). "At first we suspected that infection or autoimmune diseases could have caused the fever and high CRP level; we had doubts about their association with the gastric tumor." (PMID 28276003, 2017). "This risk of an autoimmune disease may be further quantified on the basis of gender, white blood cell count, hemoglobin level and CRP." (PMID 24180594, 2013). "Autoimmune conditions like GBS can stimulate the production of a high level of inflammation resulting in an increase in the CRP production, so highly sensitive CRP assay may become a new risk assessment marker in the future for autoimmune disorders including GBS." (PMID 29780224, 2018). "However, the association between lipid levels and cardiovascular disease risk in autoimmune disorders may be more complex than that in the general population, because systemic inflammation, such as C-reactive protein, may contribute to changes of lipid levels." (PMID 24587064, 2014). "Genetic variants encoding the different APOE isoforms have been associated with a range of inflammatory and autoimmune diseases such as Alzheimer’s disease (AD), psoriasis vulgaris, diabetic nephropathy, severity of hepatitis C infection, and levels of C-reactive protein (CRP)." (PMID 23613766, 2013).
autoimmune disease (continued). "Future studies are warranted to explore the additive clinical value of NLR alongside established biomarkers such as C-reactive protein and autoantibody panels, thereby refining its role in the early diagnosis and management of autoimmune diseases." (PMID 41495095, 2026). "The number of articles describing the relationship between lipid mediators and CBC and CRP in autoimmune diseases is very limited." (PMID 41439954, 2025). "For instance, patients with autoimmune diseases tended to have elevated C-reactive protein and lower hemoglobin, though the correlation was weak and not statistically significant in this sample." (PMID 41018357, 2025). "Although elevation of CRP is often seen in the context of any inflammation or infection, it can be used as a valuable tool to gauge the severity of an autoimmune disease exacerbation as well as patient response to treatment." (PMID 40161164, 2025). "Other ratios such as the PLR and CRP/albumin ratio have been reported to be altered in autoimmune disorders, including systemic sclerosis." (PMID 41464713, 2025). "As a result, CRP levels are commonly used to monitor infection, inflammation, and autoimmune diseases." (PMID 40573262, 2025). "CRP can be elevated in numerous conditions, but a baseline for patients with a well-controlled autoimmune disease can help determine when an exacerbation occurs, as CRP will become markedly elevated during a flare-up." (PMID 40161164, 2025). "CRP is a validated inflammatory marker used frequently in clinical set-up for various autoimmune diseases and visceral malignancies." (PMID 39851610, 2025). "First, CRP is a general marker of inflammation and is elevated in a variety of conditions, including infections, autoimmune diseases, and cardiovascular diseases." (PMID 39913250, 2025). "It has been shown to be successful in treating adverse events while reducing CRP and in preventing the exacerbation of autoimmune diseases." (PMID 41373773, 2025). "To further investigate the association of GA, PROM, antenatal steroids, maternal autoimmune diseases, delivery mode and MAS with CRP ≥ 8 mg/L, we used the multivariate logistic regression analysis method." (PMID 38302903, 2024). "Not only in CIA, CRP has also been shown to alter immune responses in animal models of other autoimmune diseases including encephalomyelitis, antigen-induced arthritis and nephritis." (PMID 38650931, 2024). "On the other hand, the concentrations of C-reactive protein (CRP) can vary under diverse insults, such as bacterial infections, tissue damage, cardiovascular alterations and autoimmune diseases, and can also be a prognostic factor." (PMID 39518437, 2024). "As expected, CRP values were significantly higher in bacterial infection compared to autoimmune disease/GVHD and controls (p < 0.0001 for both)." (PMID 38510238, 2024). "Because dogs with autoimmune diseases are often treated with high doses of glucocorticoids, a potential effect of this treatment on serum CRP concentrations—apart from the disease process—cannot be excluded." (PMID 37888572, 2023). "C-reactive protein (CRP), another inflammatory cytokine, is synthesized in the liver in response to tissue damage, microbial infection, and autoimmune diseases." (PMID 38138587, 2023). "VEXAS syndrome (vacuoles, E1 enzyme, X-linked, autoinflammatory, somatic syndrome) is supposed to be a new autoimmune disorder, and authors of a study reported elevated CRP in those with severe manifestations." (PMID 37873776, 2023). "This study confirms the association between markers of inflammation in autoimmune disease such as ESR and CRP potential subclinical atherosclerotic disease in SLE patients on cMRI." (PMID 38505536, 2023). "This action was lost in mCRP, further highlighting the complexity of regulation of immune response by CRP isomers in autoimmune diseases." (PMID 37564640, 2023).
autoimmune disease (continued). "CRP has been unequivocally listed as a key indicator of infectious and inflammatory diseases including autoimmune diseases." (PMID 37860004, 2023). "We will also discuss their therapeutic potential in mitigating the deleterious actions attributed to CRP under various pathologies, including cardiovascular, pulmonary and autoimmune diseases and cancer." (PMID 37564640, 2023). "C-reactive protein (CRP) can be measured in serum and is a useful biomarker to diagnose inflammatory conditions (e.g., autoimmune diseases) and monitor the response to treatment in dogs." (PMID 37888572, 2023). "Cytokines and C-reactive protein (CRP) are notable immune proteins that, when dysregulated, are core components in the pathogenesis of autoimmune diseases." (PMID 36793337, 2023). "Autoantibodies against CRP were discussed in the previous section; regarding its role in autoimmune diseases, CRP has thoroughly been discussed, with some authors believing that it possibly has a protective role in such conditions." (PMID 37873776, 2023). "Although CRP is widely used as a biomarker for IBD, it lacks specificity; elevated CRP levels are also observed in autoimmune disorders, infections, and malignancies." (PMID 35884797, 2022). "As we all know, CRP as an acute-phase protein is widely used in the diagnosis and treatment of autoimmune diseases or infections." (PMID 35757752, 2022). "Psoriasis is an autoimmune disease with modest systemic aberrations of IL-6, CRP, TNF-α, E-selection, and ICAM and comorbidity with SCZ." (PMID 35082268, 2022). "CRP is the most widely investigated biomarker of low-grade systemic inflammation and a risk factor for CVD disease, cancer, autoimmune disorders, and several other chronic diseases." (PMID 36558465, 2022). "For CRP, results remain unchanged using BMI as a covariate and excluding subjects with autoimmune diseases." (PMID 35013457, 2022). "CRP plays a central role in cardiovascular disease, while IL-1β plays a key role in acute and chronic inflammatory and autoimmune diseases." (PMID 36552200, 2022). "Individuals with autoimmune diseases, taking immune-modulating agents (if this information was available), or with CRP levels >4 standard deviations from the mean were excluded." (PMID 34168680, 2021). "CRP reflects ongoing inflammation and/or tissue damage across a broad range of diseases, including infections, allergic complications of infection, autoimmune diseases, and malignancies such as lymphoma, carcinoma, and sarcoma." (PMID 33298607, 2021). "C-reactive protein (CRP) is used as a general inflammatory marker in patients with autoimmune diseases." (PMID 33617568, 2021). "Free circulating CRP has been extensively studied in various settings of inflammation including autoimmune diseases and infection." (PMID 32932765, 2020). "In response to tissue injury or infection, the plasma concentrations of CRP can increase rapidly, moreover CRP level also increases in chronic inflammatory diseases, including cardiovascular and autoimmune disease." (PMID 32555600, 2020). "In autoimmune disease and immunodeficiency, higher erythrocyte sedimentation rates are seen with lower levels of CRP." (PMID 32030452, 2020). "The conjecture that the CRP levels pose protective effects in halting the autoimmune disease process needs to be further studied to find out about their significance in the obese and overweight population." (PMID 32864245, 2020). "Antibodies directed against CRP, SAP, and PTX3 have been detected in various autoimmune diseases, especially in SLE and ANCA-associated vasculitis (AAV)." (PMID 33664737, 2020). "Specifically, there is an association between ASD and maternal infection requiring hospitalization during pregnancy, elevated C-reactive protein, and a family history of autoimmune diseases." (PMID 32025243, 2020).
autoimmune disease (continued). "The combined test CRP plus ESR gave an increase of 0.014 in the AUC for autoimmune disease (P<0.001) and 0.003 increase in AUC for cancers (P = 0.006) compared with single CRP test." (PMID 31208975, 2019). "Various inflammatory biomarkers, such as ESR and CRP, are commonly used in clinical practice to supplement clinical data for determining disease activity in various autoimmune diseases and chronic infectious diseases." (PMID 31022229, 2019). "We confirmed that both ESR and CRP were also increased during active disease episodes, similar to the response of these parameters in other autoimmune diseases and unresolved bacterial infections, such as osteomyelitis." (PMID 31022229, 2019). "Currently, similar to the C-reactive protein (CRP), IL-6 is used to “monitor” inflammation levels in patients with cancer, infection, or autoimmune diseases." (PMID 31795299, 2019). "From this point of view, it is critical to identify the putative pathogens, which evoke disease markers, such as RF, ESR, CRP and anti-CCP antibody and cause hematological abnormality, and ultimately are implicated in developing autoimmune diseases." (PMID 29408886, 2018). "In contrast to sTREM-1 or CRP, PCT had a relatively higher diagnostic value in febrile patients with autoimmune diseases." (PMID 27096761, 2016). "Our study simultaneously evaluated both PCT and sTREM-1 along with C-reactive protein (CRP) in febrile patients with autoimmune diseases." (PMID 27096761, 2016). "CRP is an acute-phase reactant, and plays a role in microbial infection, trauma, infarction, autoimmune diseases, and malignant cancers." (PMID 27733196, 2016). "One study assessing the effect on CRP recruited both subjects with chronic non-autoimmune disease and subjects with chronic autoimmune disease, and after excluding this study the result concerning CRP did not change significantly." (PMID 24505395, 2014). "The acute phase reactant C-reactive protein (CRP) is widely used in clinical routine as a biomarker of inflammation in both infectious and autoimmune diseases." (PMID 24432024, 2014). "IFN produced by pDC contributes to pathogenesis of SLE and other autoimmune diseases, so these results are consistent with the protective effect of CRP in mouse models of SLE." (PMID 24167754, 2013). "In such patients, the presence of a low white blood cell count, low hemoglobin, low CRP and female gender should increase concern for a possible autoimmune disease." (PMID 24180594, 2013). "Inflammatory processes accompanying tissue injury, infection, malignancy, autoimmune diseases, and cardiovascular diseases can all result in an increase in C-reactive protein levels." (PMID 21547258, 2011). "C-Reactive Protein (CRP) is an acute phase reactant routinely used as a biomarker to assess either infection or inflammatory processes such as autoimmune diseases." (PMID 18445267, 2008). "In sharp contrast to the proposed inhibition of CRP for cardiovascular disease treatment, the infusion of CRP has been shown to have profound therapeutic benefits for autoimmune disease and septic shock." (PMID 19690638, 2007). "According to Du Clos and Mold (2004), CRP acts through Fcγ receptor to play important roles in infection, inflammation, and autoimmune diseases." (PMID 16263508, 2005). "Theselatter properties of CRP have long been suspected to contribute to homeostasis andto autoimmune disease." (PMID 15559367, 2004). "A variety of other conditions, such as inflammatory diseases, autoimmune diseases, tumors, and cardiovascular diseases, may lead to elevated CRP levels." (PMID 40313464, 2025). "Elevated biomarkers i.e., C-reactive protein (CRP) and estimated sedimentation rate (ESR) are the hallmark of diagnosis which may be associated with autoimmune disease activity." (PMID 40665038, 2025).
autoimmune disease (continued). "In our study, individuals with additional conditions that could affect CRP levels—such as chronic inflammatory diseases, active infections, autoimmune diseases, and malignancies—were excluded." (PMID 40941666, 2025). "Furthermore, moderate exercise has anti-inflammatory effects in various diseases, and meta-analyses have shown that regular exercise can reduce levels of inflammation-related markers in autoimmune diseases, such as C-reactive protein, TNF-α, and IL-6." (PMID 41347064, 2025). "Elevations in CRP, fibrinogen, and ferritin, key acute-phase reactants are characteristic of autoimmune diseases such as RA, reflecting systemic inflammation and complementing the inflammatory cascade driven by pro-inflammatory cytokines, particularly interleukin-6 (IL-6)." (PMID 40757204, 2025). "Increased levels of proinflammatory markers such as the C-reactive protein (CRP) and interleukin (IL)–6, IL-8, and tumor necrosis factor (TNF)–α are closely associated with active inflammation and disease progression in cardiovascular and autoimmune diseases." (PMID 39499914, 2024). "However, her blood test showed a mild elevation of C-reactive protein level (3.16 mg/dL), with positive IgG4 and myeloperoxidase anti-neutrophil cytoplasmic antibody results, suggesting an autoimmune disease." (PMID 38887326, 2024). "In our study, the analysis of serum levels of C-reactive protein (us-CRP), used as an important marker of inflammation because its levels are elevated in inflammatory conditions, including cardiovascular and autoimmune diseases, were detected in 8 individuals with DS." (PMID 39264098, 2024). "Results that show testosterone affects protein metabolism imply that it may also affect T2D by suppressing or enhancing immune genes related to inflammation, cytokine, and CRP levels, which are common indicators for autoimmune diseases." (PMID 36793337, 2023). "Concurrent acute or chronic infections and autoimmune diseases of subjects and the confounding effect of inflammatory markers (i.e., C-reactive protein) may have been overlooked as well." (PMID 36235661, 2022). "Besides, a preceding study investigates the correlation between MALT1 expression and clinical features in autoimmune diseases: MALT1 is positively related to CRP, TNF‐α, and IL‐17A in inflammatory bowel disease patients." (PMID 35622982, 2022). "TTR, ITIH4, C3, and CRP have been previously reported in the disease pathogenicity and inflammation of autoimmune diseases, affecting synovial joints with restricted joint movements, whereas HP has been linked with irregularity in the homeostasis of free hemoglobin in OA." (PMID 36569927, 2022). "We strove to eliminate confounding factors of CRP, such as the same treatment protocol, surgical approach, timing of CRP test, and excluding patients with pre-existing kidney or liver diseases, autoimmune diseases, concomitant infections, and spacer complications." (PMID 35626186, 2022). "Elevated CRP levels have also been attributed to certain autoimmune diseases, such as RA." (PMID 35893326, 2022). "Deceased patients respond to higher HERV-K levels increasing IL-17, a further proinflammatory mediator that may upregulate IL-6, CRP, and airway remodeling and is upregulated by HERVs in autoimmune diseases." (PMID 35459226, 2022). "Furthermore, several studies of cardiovascular and autoimmune diseases have highlighted the importance of the genetic regulation of CRP." (PMID 34945133, 2021). "Our study adds a new dimension to understand the multi-faceted effects of CRP in EAE remission, which suggests that CRP may be a novel drug target for the fundamental prevention and treatment of MS and other T-cell mediated autoimmune diseases." (PMID 33841391, 2021).